VPS35 (VPS35 retromer complex component)
Diseases named in the same sentence as VPS35 in open-access papers (continued):
Sharing a sentence is not in itself a finding about the gene and the disease.
neurodegenerative disease (continued). "Here, we develop conditional knockout mice with the selective deletion of VPS35 in neurons to better elucidate its role in neuronal viability and its connection to neurodegenerative diseases." (PMID 34704029, 2021). "We suggest VPS35 as a potential therapeutic target for PD, AD, and other neurodegenerative diseases." (PMID 33032646, 2020). "The contribution of VPS35 to several neurodegenerative diseases has been reported before." (PMID 39736627, 2024). "Indeed, Vps35, a key component of retromer cargo recognition sub-complex, has been reported as an active player in the pathogenesis of neurodegenerative diseases." (PMID 34445101, 2021). "Our results supports previous reports that dysfunctional retromer linked to neurodegenerative diseases is not primarily caused by loss of expression of Vps35 but by decreased endosomal association causing loss of function that can be mitigated by retromer stabilizing compounds such as R55 and R33." (PMID 40931359, 2025). "Other promising compounds called chaperones like heat shock proteins and vacuolar sorting protein 35 (VPS35) function by assisting other proteins to function normally and to arrive at their destination in the cell safely, and therefore can be used as a treatment for neurodegenerative diseases." (PMID 33302541, 2020). "Our study highlights that targeting VPS35 has an ameliorative effect on Aβ endocytosis and pathology and provides further evidence supporting the application of IHT for treating neurodegenerative diseases, including AD." (PMID 38831312, 2024).
tumor (14 papers, 2014 to 2026). "In this study, combining biological information analysis with in vitro cell assays and in vivo experiments, we aim to investigate the potential association between VPS35 and tumor immunity, as well as LIHC promotion." (PMID 41531939, 2026). "Pan-cancer analysis showed that VPS35 expression was positively correlated with tumor mutation burden (TMB) in 14 cancer types and microsatellite instability (MSI) in 15 cancer types." (PMID 41531939, 2026). "The results showed that the expression of VPS35 was closely associated with tumour size, T stage, N stage, vascular invasion, and AJCC stage." (PMID 37950040, 2024). "Gain- and loss-of function experiments revealed that VPS35 promoted tumour proliferation and metastasis via the IL-6/STAT3 pathway." (PMID 37950040, 2024). "In sharp contrast, transplantation of GFP+ tumor tissue from vps35 mutant larval brains caused massive tumor formation (yellow bracket) and metastasis to distal organs such as the eyes (yellow arrowhead)." (PMID 30176986, 2018). "In addition, subgroup analysis shows that high expression of VPS35 was associated with tumor status, residual tumor, histologic grade, vascular invasion, pathologic stage and pathologic T stage." (PMID 41531939, 2026). "Together, these findings suggest that VPS35 may serve as a key regulator in tumor immunity and a potential biomarker associated with immune infiltration in LIHC." (PMID 41531939, 2026). "In cancers with high VPS35 levels, this suppression of repair could create a permissive environment for mutation accumulation, accelerating tumor evolution." (PMID 40484931, 2025). "Knockdown of VPS35 led to the inhibition of scavenger receptor endocytosis and VPS35 mutation resulted in the overproliferation and excessive differentiation of haemocytes, suggesting that it might have a tumor suppressor function." (PMID 25288323, 2014). "Next, we performed immunohistochemical staining of KI67 on the tumor tissue and found that cell proliferation decreased after the knockdown of VPS35." (PMID 41531939, 2026). "This apparent contradiction underscores the complexity of VPS35's functional roles in tumor biology and cautions against an oversimplified interpretation of its therapeutic potential." (PMID 41531939, 2026). "The strong correlation between VPS35 and these signaling molecules implies a potential mechanism whereby VPS35 facilitates tumor progression by regulating critical signaling hubs." (PMID 41531939, 2026). "Knockdown of VPS35 significantly reduced the proliferation, invasion, migration of tumor cells and inhibited subcutaneous tumor formation." (PMID 41531939, 2026). "Considering that VPS35 expression was increased in tumours derived from several different tumours, we next investigated the clinical significance of VPS35 in GC patients." (PMID 37950040, 2024). "Western blot analysis showed that RGD treatment increased the level of MST1/2, LATS1 and YAP phosphorylation but markedly reversed the elevated levels of FAK, SRC and AKT phosphorylation induced by VPS35 overexpression in tumour cells." (PMID 37950040, 2024). "The results of IHC demonstrated that the expression of CDC37, GLA, HIF-1α and VPS35 was upregulated in the tumor tissues compared with corresponding normal tissues." (PMID 38528532, 2024). "In this study, we found that the expression of VPS35 was upregulated and related to poor prognosis in GC, implying that it has a potential tumour oncogenic role in GC." (PMID 37950040, 2024). "To confirm the in vitro results, we investigated the role of VPS35 in tumour growth using a xenograft model." (PMID 37950040, 2024). "Vacuolar protein sorting-associated protein 35 (VPS35) is found to be upregulated in the EVs from HCC cells when stimulated by STA9090 and can enhance tumor metastasis, primarily through the activation of the Bclaf1-VPS35-EVs axis." (PMID 39227992, 2024).
tumor (continued). "Of the 89 pairs, 54 (60.67%) had higher VPS35 protein expression in tumour stomach tissues than in nontumour tissues, and 13 (14.61%) had similar VPS35 expression in both tissue samples, whereas only 22 (24.72%) had lower VPS35 expression in tumour tissues." (PMID 37950040, 2024). "Recent studies have shown that VPS35 promotes tumor cell proliferation and affects the nuclear accumulation of its interacting partner." (PMID 35690672, 2022). "Taken together, this study provides potential mechanistic insight into the roles of VPS35 in tumor cell proliferation." (PMID 35690672, 2022). "Collectively, our data demonstrated that KLF7 promotes HCC tumor growth and invasion by stimulating the expression of VPS35." (PMID 33858520, 2021). "In summary, our study demonstrated the crucial roles of KLF7/VPS35 axis in HCC tumor growth, cell invasion, cell cycle and cell apoptosis." (PMID 33858520, 2021). "The incidence of response to the antigens, prior to the development of palpable tumor, ranged from 5% (Pdhx) to 30% of mice for Vps35 for IgG." (PMID 24886063, 2014). "In LIHC, VPS35 expression levels were significantly correlated with clinicopathological features such as the T stage, pathological stage, histological grade, vascular invasion, and residual tumor." (PMID 41531939, 2026). "Furthermore, multivariate Cox regression found that tumor status (HR = 1.83, 95% CI: 1.14–2.93, P = 0.013) and VPS35 expression (HR = 1.50, 95% CI: 1.07–2.11, P = 0.019) were independent risk factors for OS in LIHC." (PMID 41531939, 2026). "Furthermore, we also conducted experiments in animal bodies, and the results showed that the size, volume and weight of the tumor all decreased after the knockdown of VPS35." (PMID 41531939, 2026). "Furthermore, patients with higher expressions of VPS35 and HIF-1α frequently associated with larger tumor size; while higher expression of GLA was indicative of worse T stage, N stage and AJCC stage." (PMID 38528532, 2024). "Furthermore, the mRNA level of VPS35 correlated positively with tumour stage in the TCGA and GSE63288 + GSE36968 cohorts." (PMID 37950040, 2024). "Our study provides strong evidence to support the hypothesis that the VPS35/YAP/IL-6 loop bridges the interaction between tumour cells during gastric malignant progression." (PMID 37950040, 2024). "Therefore, our findings indicate that VPS35 enhances tumour proliferation and metastasis by regulating YAP activation during gastric carcinogenesis." (PMID 37950040, 2024). "Next, we explored the molecular mechanisms by which VPS35 induces YAP activation in tumour cells." (PMID 37950040, 2024). "KLF7 transcriptional activation of VPS35 was necessary for HCC tumor growth and metastasis." (PMID 33858520, 2021). "In addition, KLF7 enhanced VPS35 transcription that promoted HCC tumor growth and invasion by activating beta catenin signaling pathway." (PMID 33858520, 2021). "Loss of VPS35 inhibits scavenger receptor ligand endocytosis, causes signaling defects at the NMJ, and leads to over proliferation of blood cells in larvae, which suggests VPS35 has tumor suppressor properties." (PMID 29686647, 2018). "We next employed transplantation assay to test whether the ectopic neuroblasts in vps35 mutant brains are capable of initiating tumor." (PMID 30176986, 2018). "Importantly, the vps35 mutant GFP+ tumor cells extracted from the abdomen of transplanted hosts were Dpn+ Miranda (Mira)+ neuroblast-like cells." (PMID 30176986, 2018). "In addition, VPS35 was involved in tumor growth, invasion, and metastasis of LIHC." (PMID 41531939, 2026). "Thus vps35 mutant cells in the larval brains are indeed tumor-initiating cells." (PMID 30176986, 2018). "Our study confirmed that overexpression of VPS35, regulated by KLF7, promoted the tumor growth in vitro and in vivo, and contributed to cell invasion, cell cycle and blocked cell apoptosis." (PMID 33858520, 2021).
tumor (continued). "For VPS35 the correlation between corrected spots per well VPS35-specific IFN-g T cells and tumor size was R2 was 0.56 (p = 0.03), for APRC2 the R2 was 0.78 (p = 0.02), for SERBP1 the R2 was 0.55 (p = 0.03), and for KRT8 the R2 was 0.64 (p = 0.02)." (PMID 33976232, 2021). "Taken together, our results show that targeting VPS35- and IL-6/STAT3-mediated tumour interactions may be an attractive therapeutic strategy for GC." (PMID 37950040, 2024). "In nude mice, when VPS35 was overexpressed in NCI-N87 cells, the tumours showed enhanced growth." (PMID 37950040, 2024). "Mechanistically, VPS35 activates FAK-SRC kinases through integrin-mediated outside-in signalling, which results in the activation of YAP and, subsequently, IL-6 expression in tumour cells." (PMID 37950040, 2024).
infection (13 papers, 2014 to 2024). The state of being infected such as from the introduction of a foreign agent such as serum, vaccine, antigenic substance or organism. "Knockdown of retromer subunit VPS35 or VPS29 or infection with HPV16 PsV harboring retromer binding site mutations in L2 causes HPV accumulation in endosomes, indicating that the HPV-retromer interaction is required for endosome exit." (PMID 37703297, 2023). "Whereas depletion of either factor impairs Brucella intracellular replication, only RAB7A knockdown showed a marked effect on pathogen entry, whereas VPS35 appears to be required only at a later stage of the infection." (PMID 31243080, 2019). "We conclude that seven-day infection with all three independent shRNAs against VPS35 led to retromer dysfunction in mouse neurons." (PMID 29445238, 2018). "Infection with wild-type HPV PsV but not the HPV DM mutant caused the VPS35-positive puncta to largely co-localize with the TBC1D5-positive puncta (center and bottom rows, and S6F)." (PMID 32521275, 2020). "We evaluated the viability of rat primary cortical neurons following infection with lentiviral vectors expressing human VPS35 variants or GFP as a negative control." (PMID 24740878, 2014). "In contrast, at eight hours after infection with HPV16.L2DM, the PLA signal for L2 and Vps35 was decreased by 70% compared to cells infected with the wild-type PsV." (PMID 25693203, 2015). "Thus, we first used confocal imaging to investigate the distribution of SNX27, Vps35 and SNX1 in the early phase of infection." (PMID 39359939, 2024). "To distinguish whether the observed effects of SNX27 depletion are associated with its contribution to the SNX27:Retromer:ESCPE-1 complexes, we examined the effect of Vps35 and SNX1 + 2 depletion on the expression of pM74 in the L phase of infection." (PMID 39359939, 2024). "Indeed, depletion of VPS35 also contributed the increased infection of SARS-CoV-2 pseudovirus, although the effect of VPS35 KD is less than that of SNX27 KD." (PMID 35022217, 2022). "Thus, we decided to investigate the role of the retromer complex in trans-infection using siRNA targeting key components, VPS26A and VPS35, of the retromer complex." (PMID 32075937, 2020). "Infection with wild-type HPV16 PsV increased co-immunoprecipitation between TBC1D5 and VPS35 whereas infection with the DM mutant PsV did not (lanes 4–6)." (PMID 32521275, 2020). "Lentiviral infection of cortical cultures at days-in vitro (DIV) 3 results in the efficient and long-term transduction of the majority of cortical neurons as indicated by labeling of cultures for V5-tagged VPS35 or GFP." (PMID 24740878, 2014). "The overexpression of WT or D620N VPS35 in cortical neurons up to DIV 14 significantly increases apoptotic neuronal cell death and reduces neuronal viability compared to infection with control lentiviral vectors (empty or GFP)." (PMID 24740878, 2014). "As we have previously reported, IncE co-immunoprecipitates with FLAG-SNX5 in infected cells, and infection does not appreciably diminish steady-state levels of SNX1, VPS35, or CI-MPR." (PMID 28252385, 2017).
cancer (11 papers, 2019 to 2026). A tumor composed of atypical neoplastic, often pleomorphic cells that invade other tissues. "Given that SNXs can interact with the retromer complex to determine cargo selection, and considering that retromer dysfunction is linked to numerous diseases, including cancer, we further investigated the involvement of VPS35, a key component of the retromer complex." (PMID 40303303, 2025). "The forest map and prognostic heatmap show the prognostic value of VPS35 in a variety of cancer types." (PMID 41531939, 2026). "TMB and MSI correlation analyses showed that VPS35 expression was positively correlated with TMB in 14 cancer types and with MSI in 15 cancer types." (PMID 41531939, 2026). "As expected, IHC staining results showed that both active-β-catenin expression was higher in cancer tissues comparing with normal tissues, which revealed a strong positive correlation between expression of VPS35 and active-β-catenin in HCC samples." (PMID 33858520, 2021). "In A-431, U-2OS, and U-251MG cells, commonly used in cancer research due to their biological relevance and experimental tractability, VPS35 predominantly localized to the nucleoplasm, as indicated by green fluorescence signals colocalizing with nuclear markers." (PMID 41531939, 2026). "It is an intriguing possibility that the reduced viability of some HER2-dependent cancer cell lines upon depletion of trafficking proteins such as VPS35, Rab7 and LAMP144 might be related to alterations in HER2 trafficking." (PMID 31138794, 2019). "However, research on the potential role of VPS35 in cancer is relatively limited." (PMID 37950040, 2024). "Analysis of the CTRP and GDSC databases revealed that the VPS35 expression level was correlated with sensitivity to multiple chemotherapeutic agents (e.g., doxorubicin, BRD1812, PLX4720) across pan-cancer." (PMID 41531939, 2026).
neurological disease (4 papers, 2021 to 2024). "Although mice were grossly normal at birth and produced at normal Mendelian frequencies, neuronal VPS35 deletion caused a rapid and progressive neurological disease over ∼15 days characterized by motor deficits, impaired growth and early post-natal lethality." (PMID 34704029, 2021). "Based on these vital functions of VPS35 in the nervous system, IHT-induced modulation of VPS35 has a potential therapeutic role in numerous neurological diseases." (PMID 38831312, 2024).
mitochondrial disease (1 paper, 2022). "Interestingly, mutations in TWNK, ATAD3A, and VPS35 are linked to several severe mitochondrial diseases having in common mtDNA instability, therefore representing a cluster of proteins involved in specific mtDNA turnover." (PMID 36344526, 2022).
transmission disease (1 paper, 2019). "At the moment, four genes are known, clearly implicated in autosomal dominant Parkinson’s disease—the SNCA/PARK1–PARK4 gene, the LRRK2/PARK8 gene, the VPS35/PARK17 gene, and the EIF4G1/PARK18 gene; instead, PARK-1 and DJ-1 genes are involved in the autosomal recessive transmission disease." (PMID 31817546, 2019).
VPS35 also shares sentences with these, for which no sentence is quoted: frontotemporal dementia (5 papers); Pick disease (3); progressive supranuclear palsy (3); Anxiety (2); Blindness (2); dementia with Lewy bodies (2); memory impairment (2); Tremor (2); Akinesia (1); amyloidosis (1); autism (1); autosomal recessive intellectual disability (1); bacterial infections (1); blepharospasm (1); Bradykinesia (1); copper metabolism disorders (1); developmental delay (1); diphtheria (1); Down syndrome (1); dysautonomia (1); Dyskinesia (1); endometrial cancer (1); Gaucher disease (1); Gliosis (1); infant botulism (1); Intellectual disability (1); ischemic cardiomyopathy (1); juvenile neuronal ceroid lipofuscinosis (1); late-onset Parkinson disease (1); leukemia (1).
A further 20 diseases each share a sentence with VPS35 in 1 paper.